TSPAN9 (tetraspanin 9)
Synonyms: NET5; NET-5; PP1057
Tractability: Antibody: its Gene Ontology location is reachable by antibodies, with high confidence; UniProt predicts a signal peptide or a membrane-spanning region. PROTAC: its protein half-life has been measured.
Gene: Protein-coding gene on chromosome 12 (3,077,355 to 3,286,564, forward strand). Ensembl gene ENSG00000011105.
Subcellular location: Membrane
Subcellular location (Human Protein Atlas): Golgi apparatus; Nucleoplasm; Cytosol
Gene Ontology:
Molecular function: signaling receptor binding
Cellular component: extracellular matrix; focal adhesion; plasma membrane; tetraspanin-enriched microdomain; membrane; migrasome
Genetic constraint (gnomAD): Loss-of-function variants: 16 observed, 29.06 expected, observed/expected ratio (o/e) 0.55, 90% interval 0.37 to 0.84. The upper end of that interval is the gene's LOEUF score, 0.84, which puts it in group 3 of 6, group 1 being the genes least tolerant of losing a copy. Missense variants: 272 observed, 310.58 expected, observed/expected ratio (o/e) 0.88, 90% interval 0.79 to 0.97. Synonymous variants: 145 observed, 124.57 expected, observed/expected ratio (o/e) 1.16, 90% interval 1.02 to 1.34.
Homologues: Orthologues: macaque TSPAN9 (100% identical), chimpanzee TSPAN9 (99% identical), dog TSPAN9 (98% identical), mouse Tspan9 (97% identical), rat Tspan9 (97% identical), pig TSPAN9 (96% identical), guinea pig TSPAN9 (95% identical), tropical clawed frog tspan9 (93% identical), zebrafish tspan9a (81% identical), zebrafish tspan9b (77% identical). Paralogues in human: TSPAN4 (56% identical), CD53 (40% identical), CD151 (32% identical), CD82 (32% identical), TSPAN11 (31% identical), TSPAN18 (31% identical), TSPAN8 (31% identical), TSPAN17 (31% identical), TSPAN1 (30% identical), TSPAN5 (29% identical), CD63 (28% identical), TSPAN14 (28% identical), and 20 more.
Diseases named in the same sentence as TSPAN9 in open-access papers:
TSPAN9 is named in the same sentence as 29 diseases in open-access papers, as found by Europe PMC text mining. Sharing a sentence is not in itself a finding about the gene and the disease. The quoted sentences say what the papers report.
gastric cancer (17 papers, 2019 to 2025). A primary or metastatic malignant neoplasm involving the stomach. "Although some studies suggest an anti-cancer role for TSPAN9, high TSPAN9 expression was associated with resistance to 5-fluorouracil via suppressing autophagy in gastric cancer cell lines." (PMID 35739492, 2022). "To assess to what extent TSPAN9 is linked with gastric cancer progression, we assessed how TSPAN9 influences the epithelial-mesenchymal transition (EMT) as well as gastric cancer cell migration." (PMID 31242895, 2019). "To verify the downstream effects caused by knockout of TSPAN9, we underexpressed TSPAN9 protein in gastric cancer cells." (PMID 31242895, 2019). "Immunohistochemistry and Western blotting have shown that low levels of TSPAN9 expression were detected in clinical tumor specimens and gastric cancer cell lines, but elevated TSPAN9 expression was associated with poor prognosis, which encouraged us to conduct more in-depth research on TSPAN9." (PMID 31911756, 2020). "Previously, TSPAN9 has been reported to inhibit gastric cancer cell migration; however, the underlying molecular mechanism remains unclear." (PMID 31242895, 2019). "A latest investigation indicates that TSPAN9 boosts the resistance of gastric cancer cells to 5-FU by stimulating autophagy through the suppression of the PI3K/AKT/mTOR signaling pathway." (PMID 41347075, 2025). "Mechanistically, TSPAN9 suppresses the secretion of metastasis-associated proteins, such as MMP9, through inhibition of the ERK1/2 pathway, thereby impairing gastric cancer cell proliferation, migration and invasion." (PMID 40643467, 2025). "The majority of research predominantly concentrates on the TSPAN9 function in suppressing tumor development and progression, especially within the context of gastric cancer." (PMID 41347075, 2025). "In contrast, in gastric cancer, overexpression of Tspan9 significantly inhibited cell proliferation, with cells remaining in the G1 phase and a significant decrease in S-phase cells." (PMID 38649381, 2024). "Nevertheless, recent reports on Tspan9 have focused on its role in inhibiting the development and progression of digestive tumors, particularly gastric cancer." (PMID 38389703, 2024). "In gastric cancer, Tspan9 knockdown was followed by a significant decrease in the LC3-II/I ratio and a significant increase in SQSTM1/p62 levels." (PMID 38649381, 2024). "Recent studies of Tspan9 have highlighted its function as a suppressor of migratory, invasive, and autophagic activity in gastric cancer cells." (PMID 35280793, 2022). "Recently, EMILIN-1 was suggested to increase TSPAN9 expression in gastric cancer cell lines and form a complex with TSPAN9 to synergistically inhibit FAK/Ras/Erk pathway and suppress invasion and migration." (PMID 35739492, 2022). "Expression of TSPAN9 was significantly lower in gastric cancer tissue compared to adjacent normal gastric tissue in a cohort of 105 gastric cancer samples." (PMID 35739492, 2022). "TSPAN9 is alluded to have anti-cancer effects in gastric cancer, suppressing proliferation, invasion, and migration in gastric cancer cell lines." (PMID 35739492, 2022). "In previous studies, TSPAN9 was shown to inhibit the proliferation and migration of gastric cancer cells by enhancing autophagy." (PMID 31911756, 2020). "TSPAN9 enhance the resistance of gastric cancer to 5-fluorouracil by activating PI3K/AKT/mTOR-mediated autophagy." (PMID 33362566, 2020). "This work provides an important contribution to our understanding of the mechanism by which TSPAN9 enhances gastric cancer cell resistance to chemotherapy." (PMID 31911756, 2020). "Functional assays, such as the CCK-8 assay, were used to detect the proliferation of gastric cancer cells and the response of TSPAN9 to 5-fluorouracil (5-FU)." (PMID 31911756, 2020). "Immunoblotting was used to evaluate TSPAN9 expression in parental and drug-resistant gastric cancer cells." (PMID 31911756, 2020).
gastric cancer (continued). "The current study reveals the important role of TSPAN9 in drug resistance to 5-FU in gastric cancer." (PMID 31911756, 2020). "Experimental studies have shown that TSPAN9 inhibits proliferation, migration, and invasion of gastric cancer cells through the ERK1/2 pathway." (PMID 32411183, 2020). "Our results indicate that TSPAN9 promotes autophagy and enhances the resistance of gastric cancer cells to 5-FU by inhibiting the activation of PI3K–Akt–mTOR signaling." (PMID 31911756, 2020). "At the same time, we found that high levels of TSPAN9 contribute to increased autophagy in gastric cancer cells." (PMID 31911756, 2020). "To clarify the molecular mechanism of EMILIN1 and TSPAN9, we overexpressed TSPAN9 and EMILIN1 + TSPAN9 in gastric cancer cells, respectively." (PMID 31242895, 2019). "We observed negative TSPAN9 staining was noted in 39 of the 120 (32.5%) samples assessed from gastric cancer patients, while 81 of 120 (67.5%) samples of normal gastric tissue stained positive for TSPAN9 expression." (PMID 31242895, 2019). "TSPAN9 expression was determined by RT-PCR, western blot analysis, and immunohistochemistry in gastric cancer and tumor-adjacent tissues." (PMID 31242895, 2019). "We found that TSPAN9 can disrupt gastric cancer cell invasion and migration, and EMILIN1 can synergistically promote the anti-cancer effects of TSPAN9." (PMID 31242895, 2019). "Together, these results indicate that only low levels of TSPAN9 are in gastric cancer cells as well as in tissue samples." (PMID 31242895, 2019). "TSPAN9 expression and the invasion and metastasis of gastric cancer cells were observed by the functional assays following EMILIN1 over-expression." (PMID 31242895, 2019). "Inhibiting TSPAN9 expression significantly promoted the migration and invasion of gastric cancer cells." (PMID 31242895, 2019). "From this we can conclude that low TSPAN9 expression can promote gastric cancer cell invasion and migration via FAK-RAS-ERK1/2 signaling." (PMID 31242895, 2019). "It was further found that the simultaneous high expression of TSPAN9 and EMILIN1 was more inhibitory of gastric cancer cell migration and invasion than was the overexpression of TSPAN9 alone." (PMID 31242895, 2019). "EMILIN1 synergistically regulates gastric cancer cell invasion and metastasis by promoting TSPAN9 expression." (PMID 31242895, 2019). "We then used immunohistochemistry to confirm TSPAN9 expression in gastric cancer tissue samples from patients." (PMID 31242895, 2019). "We have demonstrated that EMILIN1 induces anti-tumor effects by up-regulating TSPAN9 expression in gastric cancer." (PMID 31242895, 2019). "We then performed immunofluorescence measurements of EMILIN1 and TSPAN9 in cells and found that they co-localized in gastric cancer cell." (PMID 31242895, 2019). "Here, we demonstrate that the expression of the membrane protein TSPAN9 regulates gastric cancer cell migration and invasion by inhibiting the FAK-RAS-ERK1/2 signaling pathway." (PMID 31242895, 2019). "Additionally, Elastic Microfibril Interface Located Protein 1 (EMILIN1) can synergistically inhibit gastric cancer cell invasion and metastasis through enhancing TSPAN9 expression." (PMID 41347075, 2025). "Prior evidence also suggests that Tspan9 can suppress the development of gastric cancer." (PMID 35280793, 2022). "When Tspan9 expression was knocked down in OS cells, this suppressed their viability and proliferation, suggesting that Tspan9 plays an oncogenic role distinct from its function as a tumor suppressor in gastric cancer." (PMID 35280793, 2022). "Elucidation of these molecular and cellular mechanisms may present EMILIN-1 and TSPAN9 as new therapeutic targets in gastric cancer." (PMID 35739492, 2022). "Prior research has indicated that Tspan9 can play an anti-oncogenic function in gastric cancer." (PMID 35280793, 2022).
gastric cancer (continued). "The opposite effect of this dual gene signature in adrenocortical carcinoma, kidney renal papillary cell carcinoma, and mesothelioma led us to identify ITGA4, EMILIN11, and TSPAN9 as interactors that potentiate the poor prognostic effect of CAFs specifically in gastric cancer." (PMID 35739492, 2022). "A similar mechanism may explain the context-dependent role of EMILIN-1 and TSPAN9 in gastric cancer." (PMID 35739492, 2022). "One limitation to the study may be that only the TIDE algorithm predicted a poor prognostic impact for CAF infiltration in COL1A1, COL5A1, ITGA4, EMILIN1, and TSPAN9 multivariate Cox model in gastric cancer." (PMID 35739492, 2022). "We have demonstrated that TSPAN9 induces 5-FU resistance by increasing autophagy in gastric cancer." (PMID 31911756, 2020). "To verify whether phosphorylation is required for TSPAN9 to interact with p55, we constructed a TSPAN9-mutant plasmid in which tyrosine was replaced with asparagine (Y153D) and transfected this plasmids into gastric cancer cells." (PMID 31911756, 2020). "According to the analysis of the Oncomine public database, we found that TSPAN5 is highly expressed in liver cancer and colon cancer, TSPAN26 is highly expressed in liver cancer and gastric cancer, and TSPAN9, TSPAN28, and TSPAN29 are highly expressed in gastric and colon cancer." (PMID 32694936, 2020). "Therefore, we inhibited autophagy using the autophagy inhibitor 3-MA and observed inhibition of the protective effect of TSPAN9 on gastric cancer cells." (PMID 31911756, 2020). "Furthermore, we analyzed TSPAN9 expression in gastric cancer cells and 5-FU-resistant gastric cancer cells and found that it was high in drug-resistant cells, which led us to further explore this phenomenon." (PMID 31911756, 2020). "TSPAN9 expression was markedly reduced in gastric cancer cells following TGF-β1 treatment." (PMID 31242895, 2019). "Furthermore, the extracellular matrix glycoprotein elastin microfibril interfacer 1 (EMILIN1) may exert a synergistic effect with Tspan9 on the migration and invasion of gastric cancer cells." (PMID 38389703, 2024). "A recent study reported that the action of EMILIN-1 to inhibit the MAPK pathway and suppress proliferation in gastric cancer cells might depend on Tetraspanin9 (TSPAN9), which is a member of the tetraspanin family membrane receptors with four transmembrane domains." (PMID 35739492, 2022). "Therefore, TSPAN9 inhibitors are shedding light for 5-FU-resistant gastric cancer patients." (PMID 34222025, 2021). "Therefore, we have highlighted that TSPAN9 and other tetraspanins may represent novel therapeutic targets for the treatment of gastric cancer." (PMID 31911756, 2020). "In addition, TSPAN9 also significantly promoted autophagy in gastric cancer cells in vitro." (PMID 31911756, 2020). "According to our previous studies, TSPAN9 regulates the protein secretion levels associated with tumor metastasis, such as matrix metalloproteinase-9(MMP-9) through the ERK1/2 pathway, thereby inhibiting gastric cancer cell proliferation, migration, and invasion." (PMID 31242895, 2019). "By binding to p55, Tspan9 suppresses the activation of PI3K/Akt/mTOR signaling and promotes cell autophagy in gastric cancer, thereby inhibiting the resistance of cancer cells to 5-fluorouracil." (PMID 38389703, 2024). "The overexpression of Tspan9 can also impair FAK-Ras-ERK signaling and EMT induction to hamper metastatic gastric cancer progression." (PMID 35280793, 2022). "Taken together, CD81, CD82, TSPAN5, TSPAN9, and TSPAN21 are regarded as tumor suppressors in gastric cancer to inhibit tumor cell growth and invasion, and enhance the sensitivity to apoptotic stress signals." (PMID 34222025, 2021). "We also discuss several tetraspanins, including CD81, CD82, TSPAN5, TSPAN9, and TSPAN21 that suppress gastric cancer cell growth." (PMID 34222025, 2021).
gastric cancer (continued). "In the present study, we demonstrate that TSPAN9 blocks PI3K–Akt–mTOR signaling by interacting with PI3K, which enhances autophagy and leads to 5-FU resistance in gastric cancer cells." (PMID 31911756, 2020). "According to studies by DErrico and Cho, we found that the expression of TSPAN4, TSPAN9, TSPAN28, and TSPAN29 was higher in gastric cancer patients than it was in the normal population." (PMID 32694936, 2020). "In conclusion, this study showed that TSPAN9 and PI3K bind to each other in gastric cancer cells, which inhibits the activity of the PI3K–Akt–mTOR pathway and consequently enhances the level of autophagy and promotes 5-FU resistance." (PMID 31911756, 2020). "Following the over-expression and knockdown of TSPAN9, wound healing and cell invasion assays were performed and EMT-related protein expression was evaluated to analyze the invasion and migration of gastric cancer cells." (PMID 31242895, 2019). "Tspan9 overexpression has been found to suppress the secretion of MMP9 and urokinase plasminogen activator (uPA) by inactivating the ERK1/2 signaling pathway, ultimately inhibiting the metastasis and proliferation of gastric cancer cells." (PMID 38389703, 2024). "In general, the expression of TSPAN8, CD151, TSPAN1, and TSPAN4 is increased in gastric cancer tissues and enhance the proliferation and invasion of gastric cancer cells, while CD81, CD82, TSPAN5, TSPAN9, and TSPAN21 are downregulated and suppress gastric cancer cell growth." (PMID 34222025, 2021). "Especially, TSPAN9 expression is significantly decreased in gastric cancer tissues compared with the adjacent non-cancerous tissues but the high expression of TSPAN9 is associated with a poor prognosis." (PMID 34222025, 2021). "In particular, the role of TSPAN9 in cancer has not been thoroughly explored: a lower level of expression in gastric cancer than in non-neoplastic gastric tissue, and some anti-tumour effects in vitro gastric models, are the only findings reported so far." (PMID 32019179, 2020). "Using qRT-PCR and western blotting, we therefore assessed TSPAN9 expression in gastric cancer cells, with normal human GES-1 cells as a non-cancerous control line." (PMID 31242895, 2019). "Members of the TSPAN family have been shown to be overexpressed in some tumor cells, but currently there is no report on TSPAN9 expression in gastric cancer." (PMID 31242895, 2019). "Therefore, we tested whether the addition of TSPAN9 to the CO1A1, COL5A1, ITGA4, and EMILIN1 Cox model can decrease the poor prognostic impact of CAF infiltration in gastric cancer." (PMID 35739492, 2022). "Therefore, in assessing the anti-cancer effects of TSPAN9 and the downstream mechanism, this study found that TSPAN9 disrupts gastric cancer cell invasion and migration by inhibiting the FAK-RAS-ERK1/2 pathway by over-expressing and knocking down TSPAN9 in gastric cancer cells in vitro." (PMID 31242895, 2019). "Hence, membrane proteins TSPAN9 and EMILIN1 may represent novel therapeutic targets for the treatment of gastric cancer." (PMID 31242895, 2019). "Therefore, whether EMILIN1 and TSPAN9 exert an anti-tumor effect or pro-tumorigenic effect in gastric cancer is not clear yet." (PMID 35739492, 2022). "Since overexpression of only EMILIN1 did not induce a similar anti-tumor response in gastric cancer cell lines, it was suggested that the anti-tumor effect of EMILIN-1 may be dependent on TSPAN9." (PMID 35739492, 2022).
hepatocellular carcinoma (5 papers, 2022 to 2025). A malignant tumor that arises from hepatocytes. "For instance, in hepatocellular carcinoma (HCC), TSPAN9 appears to be more prominently associated with migrasome activity, whereas in colorectal cancer (CRC), CD151 emerges as a central player." (PMID 40299331, 2025). "The expression of TSPAN9 in hepatocellular carcinoma was significantly lower than that in adjacent non-hepatocellular carcinoma tissues." (PMID 37752917, 2023). "Patients with TSPAN9-positive hepatocellular carcinoma had relatively higher overall and disease-free survival and a better prognosis." (PMID 37752917, 2023). "The expression of TSPAN9 in hepatocellular carcinoma was negatively correlated with the level of immune cell infiltration, which was also an important factor affecting tumor treatment." (PMID 37752917, 2023). "Therefore, we determined the relationship between TSPAN9 expression in immune cell infiltration and immune checkpoints in hepatocellular carcinoma in our previous study." (PMID 37752917, 2023). "However, there is no study in revealing the aspects of TSPAN9 traits and its functions in hepatocellular carcinoma (HCC) prognosis." (PMID 35600044, 2022).
colorectal cancer (4 papers, 2020 to 2025). A primary or metastatic malignant neoplasm that affects the colon or rectum. "Tspan9 also plays a role in other digestive tract tumors, such as colorectal cancer and liver cancer." (PMID 38389703, 2024).
osteosarcoma (3 papers, 2022 to 2024). A usually aggressive malignant bone-forming mesenchymal neoplasm, predominantly affecting adolescents and young adults. "This is consistent with the reported roles of TSPAN9 in the promotion of cancer cell motility, invasion, and metastasis in osteosarcoma." (PMID 38255741, 2024). "Among them, TSPAN9 has been shown to promote osteosarcoma metastasis and affect the prognosis of breast cancer patients." (PMID 36620585, 2022).
viral infections (3 papers, 2013 to 2024). "Since the association of pDC with viral infections, maybe we can associate pDC with HBV in HCC through TSPAN9." (PMID 35600044, 2022). "Furthermore, Tspan9 promotes virus transport and membrane fusion during early α-virus infection (such as Sindbis virus and Semliki Forest virus) through the regulation of the early endosome compartment, suggesting that Tspan9 may represent an effective antiviral therapeutic target." (PMID 38389703, 2024). "TSPAN9 was identified in a broad endocytosis screen but has no known roles in promoting virus infection." (PMID 24367265, 2013).